EGFL8 (EGF like domain multiple 8)
Synonyms: C6orf8; NG3
Tractability: Antibody: UniProt places it where antibodies can reach, with high confidence; UniProt predicts a signal peptide or a membrane-spanning region; its Gene Ontology location is reachable by antibodies, with medium confidence.
Gene: Protein-coding gene on chromosome 6 (32,163,918 to 32,168,453, forward strand). Ensembl gene ENSG00000241404.
Subcellular location: Secreted
Subcellular location (Human Protein Atlas): Vesicles; Nuclear speckles; Predicted to be secreted
Gene Ontology:
Molecular function: protein binding; signaling receptor binding; calcium ion binding
Biological process: in utero embryonic development; vasculogenesis
Cellular component: cell surface; extracellular region
Genetic constraint (gnomAD): Loss-of-function variants: 33 observed, 40.44 expected, observed/expected ratio (o/e) 0.82, 90% interval 0.62 to 1.09. The upper end of that interval is the gene's LOEUF score, 1.09, which puts it in group 4 of 6, group 1 being the genes least tolerant of losing a copy. Missense variants: 385 observed, 411.14 expected, observed/expected ratio (o/e) 0.94, 90% interval 0.86 to 1.02. Synonymous variants: 177 observed, 169.86 expected, observed/expected ratio (o/e) 1.04, 90% interval 0.92 to 1.18.
Homologues: Orthologues: pig EGFL8 (87% identical), rabbit EGFL8 (84% identical), dog EGFL8 (81% identical), mouse Egfl8 (80% identical), guinea pig EGFL8 (79% identical), rat Egfl8 (74% identical), tropical clawed frog egfl8 (41% identical). Paralogues in human: EGFL7 (37% identical), CRIPTO (12% identical), CRIPTO3 (12% identical), CFC1 (11% identical), CFC1B (11% identical).
Diseases named in the same sentence as EGFL8 in open-access papers:
EGFL8 is named in the same sentence as 21 diseases in open-access papers, as found by Europe PMC text mining. Sharing a sentence is not in itself a finding about the gene and the disease. The quoted sentences say what the papers report.
neuroblastoma (3 papers, 2021 to 2024). Neuroblastoma (NB) is the most common solid, extracranial childhood tumor. "Further studies revealed that nerve growth factor (NGF) and epidermal growth factor-like protein 8 (EGFL8) are able to induce neuroblastoma differentiation and hence inhibit tumor proliferation." (PMID 39199637, 2024). "Neuroblastoma cells exposed to repaired SCs showed increased differentiation and reduced proliferation, with EGFL8 identified as a key factor promoting neurogenesis." (PMID 39796130, 2024). "Importantly, neuroblastoma cells respond to repair-related SCs increasing neuronal differentiation and reducing proliferation via EGFL8." (PMID 33712610, 2021). "Furthermore, EGFL8 exerts an antiproliferative effect on neuroblastoma cells, and higher EGFL8 expression in peripheral neuroblastic tumors correlates with improved clinical outcomes and significantly higher 5-year overall survival rates, potentially owing to its neuritogenic effect." (PMID 39796130, 2024).
colorectal cancer (2 papers, 2021 to 2024). A primary or metastatic malignant neoplasm that affects the colon or rectum. "Notably, EGFL8 expression is downregulated in gastric and colorectal cancers, and this downregulation is significantly correlated with peritoneal dissemination and high tumor–node–metastasis (TNM) stage, highlighting its potential role in cancer development." (PMID 39796130, 2024).
gastric cancer (2 papers, 2020 to 2021). A primary or metastatic malignant neoplasm involving the stomach. "Our previous studies have reported the down-regulation of EGFL8 correlates to the development and prognosis of colorectal and gastric cancer." (PMID 34130659, 2021). "However, compared with normal tissues, the expression level of EGFL8 is significantly reduced in colorectal cancer (CRC) tissues and gastric cancer tissues." (PMID 33391349, 2020).
hepatocellular carcinoma (2 papers, 2021 to 2024). A malignant tumor that arises from hepatocytes. "The present study is carried out to explore the expression pattern and role of EGFL8 in hepatocellular carcinoma (HCC)." (PMID 34130659, 2021).
liver cancer (1 paper, 2021). An epithelial or non-epithelial malignant neoplasm that arises from the liver. "Interestingly, the expression levels of EGFL8 in three liver cancer cell lines were negatively associated with their metastatic capacity." (PMID 34130659, 2021). "Of particular interest is the relationship between EGFL8 down-regulation and the metastatic capacity of these liver cancer cell lines." (PMID 34130659, 2021). "Since the expression of EGFL8 correlated with the metastatic potential of liver cancer cells, we firstly investigated the effects of EGFL8 on HCC cell migration and invasion." (PMID 34130659, 2021). "Since the in vitro data suggesting a role of EGFL8 in metastasis of liver cancer cells, we further detected the lung metastasis of HCCLM3 cells in these mice." (PMID 34130659, 2021). "RT-qPCR results showed that the expression levels of EGFL8 in three liver cancer cell lines were also significantly lower than that in HL-7702 liver cell line." (PMID 34130659, 2021). "We also determined the expression pattern of EGFL8 in a normal liver cell line and three liver cancer cell lines with different metastatic abilities by RT-qPCR." (PMID 34130659, 2021). "EGFL8 expression declined in these three liver cancer cell lines in the order by their metastatic potential descending, suggesting an obviously involvement of EGFL8 in the metastasis of HCC." (PMID 34130659, 2021). "The expression of EGFL8 were all down-regulated in all three liver cancer cell lines compared with the normal liver cell line, which confirmed the down-regulation of EGFL8 in HCC tissues." (PMID 34130659, 2021). "However, our results indeed showed a weakly promotive effect of EGFL8 on the apoptosis of liver cancer cells." (PMID 34130659, 2021). "We therefore presumed that EGFL8 might regulate the metastasis and apoptosis of liver cancer cells through inhibiting the Notch signaling pathway." (PMID 34130659, 2021). "EGFL8 expression in 102 cases of HCC tissues matched with adjacent non-tumorous liver tissues, a normal liver cell line and three liver cancer cell lines with different metastatic capacity was detected by reverse transcription-quantitative polymerase chain reaction (RT-qPCR) and Western blot." (PMID 34130659, 2021).
liver fibrosis (1 paper, 2022). "Previous studies have shown that Notch signaling pathway was related to the pathogenesis of liver fibrosis, and EGFL8 regulated HCC cell migration, invasion, and apoptosis via the activation of Notch signaling pathway." (PMID 36339006, 2022).
ovarian carcinoma (1 paper, 2024). A malignant neoplasm originating from the surface ovarian epithelium. "Therefore, our findings that EGFL8 knockdown enhances the spheroid growth of human ovarian cancer cells suggest that EGFL8 plays a critical role in suppressing spheroidogenesis and, consequently, inhibiting the malignant progression of these cells." (PMID 39796130, 2024).
tumor (12 papers, 2013 to 2024). "In contrast, compared with other infiltrate types, the correlation between the high expression of EGFL8 and C5 was observed, suggesting that EGFL8 was associated with a favorable immune component, indicating that EGFL8 may mainly act as a tumor suppressor." (PMID 33391349, 2020). "Our results further showed that EGFL8 down- regulation correlated significantly to multiple tumor nodes (P = 0.019), vein invasion (P = 0.012), and high TNM stage (P = 0.031) of HCC." (PMID 34130659, 2021). "Among the factors released by SCs, we identified the matricellular protein EGFL8 and report its neuritogenic effect on neuroblastic tumor cells." (PMID 33712610, 2021). "In recent years, several studies have shown that EGFL6, EGFL7, and EGFL8 play a crucial role in the process of tumor growth, invasion, and distant metastasis." (PMID 33391349, 2020). "On the basis of the ESTIMATE algorithm, EGLF6, EGFL7, and EGFL8 were also related to the different degrees of tumor-stromal cell and immune cell infiltrates." (PMID 33391349, 2020). "Further, our proteomic analysis confirmed the high expression levels of the EGFL8 in DFTD tumor cells." (PMID 30645971, 2019). "As EGFL8 exerted anti-tumor activity on NB cells in vitro, we next assessed whether EGFL8 expression levels in peripheral neuroblastic tumors may correlate with the clinical outcome." (PMID 33712610, 2021). "Two different datasets, comprising 649 and 283 tumor specimens, respectively, demonstrated an over 90% and 70%, respectively, 5-year overall survival probability for patients with high EGFL8 expression, but less than 60% and 40%, respectively, for patients with low EGFL8 expression." (PMID 33712610, 2021). "In addition, EGFL6, EGFL7, and EGFL8 were found to be related to immune subtypes and tumor microenvironment." (PMID 33391349, 2020). "In addition, large differences were observed in the expression levels of EGFL6, EGFL7, and EGFL8 among different tumor types and compared with normal tissues (P < 0.05)." (PMID 33391349, 2020). "Therefore, EGLF6, EGFL7, and EGFL8 had a significantly negative association with tumor stem cell-like features measured by DNAs and RNAs; however, their negative correlation in RNAs was not prominent and only manifested in individual tumors." (PMID 33391349, 2020). "Differential analysis of tumor versus healthy biopsies highlighted 166 candidate genes with different DNA methylation levels in their promoters, which included the tumor-specific hypomethylated EGFL8 promoter as well as hypermethylated promoters of ESR1, PTGIS, and GATA3." (PMID 30645971, 2019). "We also found suggestive evidence for association of top SNPs with the expression of EGFL8, which has previously been implicated in cancer progression, and NCR3, a gene that encodes a natural cytotoxicity receptor that may aid NK cells in lysing tumor cells." (PMID 23326239, 2013). "This was confirmed by immunostaining illustrating SOX10 and EGFL8 co-expression by repair SCs in injured nerve tissue and stromal SCs in GNs, while EGFL8 was absent on tumor cells in GN and NB primary tumors." (PMID 33712610, 2021).
cancer (5 papers, 2013 to 2024). A tumor composed of atypical neoplastic, often pleomorphic cells that invade other tissues. "To elucidate the role of EGFL8 in cancer stemness, we analyzed the expression of genes associated with cancer stemness." (PMID 39796130, 2024). "EGFL8 knockdown in human OC cells promoted aggressive traits associated with cancer progression, including enhanced proliferation, colony formation, migration, invasion, chemoresistance, and reduced apoptosis." (PMID 39796130, 2024). "In conclusion, this study demonstrated that the siEGFL8-mediated knockdown of EGFL8 in human OC cells promoted aggressive traits linked to cancer progression, including increased proliferation, colony formation, migration, invasion, chemoresistance, and reduced apoptosis." (PMID 39796130, 2024). "The association between EGFL8 and survival advantage or disadvantage differed in the cancer types." (PMID 33391349, 2020). "Overall, this study provides crucial evidence that EGFL8 inhibits the proliferation and cancer aggressiveness of human OC cells by suppressing ERK/MAPK signaling." (PMID 39796130, 2024). "This study aimed to investigate the role of epidermal growth factor-like domain 8 (EGFL8) in human OC by examining the effects of siRNA-mediated EGFL8 knockdown on cancer progression." (PMID 39796130, 2024). "Taken together, these findings suggest that EGFL8 expression is altered during cancer development and has a prognostic value in human OC." (PMID 39796130, 2024). "Collectively, these results demonstrate that EGFL8 negatively regulates human OC cell growth and malignant progression, highlighting EGFL8’s potential in developing new anti-cancer drugs and targeted therapies for human OC." (PMID 39796130, 2024). "The expression levels of EGFL8 were relatively lower among all cancer types than that of EGFL6 and EGFL7, with EGFL7 having the highest level of expression." (PMID 33391349, 2020). "Therefore, EGFL8 negatively regulates human OC cell proliferation and cancer aggressiveness by inhibiting the ERK/MAPK signaling pathway." (PMID 39796130, 2024). "However, despite these findings, the role of EGFL8 in cancer remains largely unknown, particularly in human OC, where its specific function is yet to be elucidated." (PMID 39796130, 2024). "Notably, EGFL8 had a negative association with RNAs and DNAs (P < 0.001), and EGFL8 had the strongest correlation with DNAs (r = -0.89) in all cancer types." (PMID 33391349, 2020). "EGFL6 had the highest correlation with the stromal score among all cancer types (r = 0.71, P < 0.001), following with EGFL7 (r = 0.65, P < 0.001) and EGFL8 (r = 0.19, P < 0.001)." (PMID 33391349, 2020). "The results showed that the expression of EGFL8 was lower than EGFL6 and EGFL7 among all cancer types, wherein EGFL7 had the highest expression." (PMID 33391349, 2020).
EGFL8 also shares sentences with these, for which no sentence is quoted: diabetes (2 papers); breast carcinoma (1); cholesteatoma (1); coronary heart disease (1); diarrheal disease (1); inflammatory skin disorder (1); invasive carcinoma (1); ischemic stroke (1); kidney disease (1); lung carcinoma (1); psoriasis (1); respiratory infection (1).